IDH2 (isocitrate dehydrogenase (NADP(+)) 2)
Diseases named in the same sentence as IDH2 in open-access papers (continued):
Sharing a sentence is not in itself a finding about the gene and the disease.
anemia (2 papers, 2019 to 2023). A reduction in the number of red blood cells, the amount of hemoglobin, and/or the volume of packed red blood cells.
chondroma (2 papers, 2014 to 2022). A benign well circumscribed neoplasm of hyaline cartilage arising from bone or soft tissue. "Since IDH1/IDH2 mutations were detected in both isolated chondromas and tumors removed from patients with multiple lesions (OD/MS)." (PMID 35765075, 2022).
clear cell renal cell carcinomas (2 papers, 2017 to 2018). "Interestingly, IDH2 could not be identified in all 10 cases of eosinophilic variants of clear cell renal cell carcinomas." (PMID 30116406, 2018). "Studying IDH1/2 mutations in clear cell renal cell carcinomas (RCCs) demonstrated that IDH1 is mutated in only 4 of 833 cases (0.5%) and no IDH2 mutations." (PMID 28403884, 2017).
cutaneous T cell lymphoma (2 papers, 2020 to 2023). "Although both cell lines (HuT78 and HH) derived from CD4+ cutaneous T-cell lymphomas are probably similar to normal CD4+ T cells, they lack mutations in TET2, DNMT3A, and IDH2 in contrast with the neoplastic cells of AITL." (PMID 37370838, 2023).
developmental delay (2 papers, 2016 to 2025). "In D2HGA, IDH2 and D2HGDH mutations both result in 2HG accumulation, accompanied by developmental delay, hypotonia and seizures, although there are phenotypic differences between the two types." (PMID 27469509, 2016).
esophageal squamous cell carcinoma (2 papers, 2019). Esophageal squamous cell carcinoma (ESCC) is a type of esophageal carcinoma (EC) that can affect any part of the esophagus, but is usually located in the upper or middle third. "IDH2 protein expression levels are significantly upregulated in esophageal squamous cell cancer (ESCC) tissues than in paracancerous tissues." (PMID 31010244, 2019).
Esthesioneuroblastoma (2 papers, 2022 to 2025). "The NEC-like IDH2 class (n = 48) contained tumors that had initially been diagnosed as either SNUCs, olfactory neuroblastomas, neuroendocrine carcinomas or adenocarcinomas." (PMID 36443295, 2022). "The neuroectodermal differentiation of specimens from the NEC-like IDH2 (FDR < 0.001) and NEC-like SMARCA4/ARID1A class (FDR < 0.001) as well as olfactory neuroblastomas (FDR < 0.001) was reflected in their similarity with pulmonary neuroendocrine cells (PNEC)." (PMID 36443295, 2022). "Furthermore, olfactory neuroblastomas (FDR 0.004) and tumors from the NEC-like IDH2 group (FDR < 0.001) showed similarity to a class of Undefined Rare Cells, which likely represent progenitor cells of epithelial and neuroendocrine cells." (PMID 36443295, 2022). "In contrast, cytokeratin 18 (KRT18) was strongly overexpressed in both NEC-like IDH2 and NEC-like SMARCA4/ARID1A cancers but not in olfactory neuroblastoma." (PMID 36443295, 2022).
giant cell tumor of bone (2 papers, 2021 to 2022). "Intrahepatic cholangiosarcoma have a high incidence of IDH1 mutations as do chondrosarcomas, with giant cell tumour/osteoclastoma dominated by IDH2 mutations." (PMID 34854890, 2021). "IDH2 mutations are more common in Acute myeloid and B-cell acute lymphoblastic leukaemia (20–33%), and cartilaginous bone tumours such as giant cell tumour of bone/osteoclastoma (80%) and osteosarcoma (28%)." (PMID 34854890, 2021).
Hearing impairment (2 papers, 2018 to 2019). A decreased magnitude of the sensory perception of sound. "Here, we report that loss of Idh2 accelerates age-related hearing loss, the most common form of hearing impairment, in male mice." (PMID 29567975, 2018). "Therefore, Idh2−/− mice could be used as a valuable animal model to evaluate the therapeutic effects of various antioxidant candidates to overcome ROS-induced hearing loss." (PMID 30508699, 2019). "Moreover, the hair cell degeneration caused by IDH2 deficiency can be prevented by MitoQ, which suggests that Idh2−/− mice could be a valuable animal model for evaluating the therapeutic effects of various antioxidant candidates to overcome ROS-induced hearing loss." (PMID 30508699, 2019).
Insulin resistance (2 papers, 2024 to 2025). Increased resistance towards insulin, that is, diminished effectiveness of insulin in reducing blood glucose levels. "Research has revealed that IDH2 knockout results in insulin resistance (IR) and suppressed hepatic lipogenesis and inflammation." (PMID 39459528, 2024).
ischemia (2 papers, 2019 to 2022). A hypoperfusion of the BLOOD through an organ or tissue caused by a PATHOLOGIC CONSTRICTION or obstruction of its BLOOD VESSELS, or an absence of BLOOD CIRCULATION. "This is the case of SUCLA2 and DLD, which were down-regulated during ischemia and not recovered after revascularization, and the isocitrate dehydrogenase components IDH3A and IDH2, which were found to be down-regulated after the re-establishment of coronary blood flow." (PMID 35216205, 2022).
kidney tumors (2 papers, 2018 to 2024). "The L-2HG enantiomer also presents oncometabolic DNA demethylation inhibitory effects in kidney tumors, however this is due to changes in L-2HG dehydrogenase rather than IDH1/IDH2." (PMID 29922517, 2018).
non-small cell lung carcinoma (2 papers, 2021 to 2024). A group of at least three distinct histological types of lung cancer, including non-small cell squamous cell carcinoma, adenocarcinoma, and large cell carcinoma. "IDH2 was also reported as a diagnostic and prognostic serum biomarker for non-small-cell lung cancer." (PMID 34557266, 2021).
NUT carcinoma (2 papers, 2014 to 2023). "There were 25 IDH2-mutant, 41 NUT carcinoma, 187 SWI/SNF loss, and 25 triple negative SNCs." (PMID 36937407, 2023). "Compared to IDH2-mutant, SWI/SNF loss, and triple negative groups, NUT carcinoma presented a significantly younger age (p < 0.001)." (PMID 36937407, 2023). "Most IDH2-mutant SNCs were originally diagnosed as SNUC whereas the diagnosis of NUT carcinoma is usually more straightforward." (PMID 36937407, 2023). "We included 61 studies with 278 SNCs including 25 IDH2-mutant, 41 NUT carcinoma, 187 SWI/SNF loss, and 25 triple negative SNCs (without IDH2 mutation, NUTM1 rearrangement, and SWI/SNF inactivation) for analyses." (PMID 36937407, 2023).
osteoblastic osteosarcoma (2 papers, 2013 to 2025). A conventional osteosarcoma characterized by the predominance of osteoid matrix. "A pathogenic IDH2 mutation was identified in 1 patient with osteoblastic osteosarcoma." (PMID 40144205, 2025).
pancreatic cancer (2 papers, 2023 to 2024). "Major mitochondrial genes including MT-ND3, MT-CO1, IDH2, and TFAM are being reported in various pancreatic cancers, including PDAC (based on cBioportal data), but their actual roles in PDAC progression need further validation." (PMID 36831413, 2023).
paraganglioma (2 papers, 2019). A benign or malignant neoplasm arising from paraganglia located along the sympathetic or parasympathetic nerves. "For example, we identified a somatic IDH2 hot spot mutation (Arg172Gly) in a paraganglioma sample." (PMID 31212687, 2019).
pituitary adenoma (2 papers, 2019 to 2022). "Take growth hormone-secreting pituitary adenomas as an example, we revealed that IDH2 is a key player in the reprogrammed metabolism of such tumors." (PMID 31455412, 2019).
spindle cell hemangioma (2 papers, 2015 to 2025). Spindle cell hemangioma (SCH), also known as spindle cell hemangioendothelioma, is a rare benign vascular tumor either solitary or multiple, characterized by cavernous blood vessels separated by spindle cells reminiscent of those in KaposiBs sarcoma and located in the dermis and subcutis. "Recent molecular studies have identified IDH1 and IDH2 gene mutations in both enchondromas and spindle cell hemangiomas associated with MS." (PMID 40894918, 2025).
acute myocardial infarction (1 paper, 2023). Necrosis of the myocardium, as a result of interruption of the blood supply to the area. "They analyzed mitochondrial isocitrate dehydrogenase (IDH2) genetic isoforms and their variations were found to be an independent risk factor for acute myocardial infarction." (PMID 37441709, 2023).
age (1 paper, 2021). A temporal measurement of the time period elapsed since an identifiable point in the life cycle of an organism.
alcoholic fatty liver disease (1 paper, 2022). Lipid infiltration of the hepatic parenchymal cells that is due to alcohol abuse. "We plan to enhance the originality of the disease mechanism through hepatocyte-specific IDH2 & miR204 double-deficient mice and study the association of miR204 / IDH2 in samples obtained from patients with non-alcoholic fatty liver disease." (PMID 36130994, 2022).
atherosclerosis (1 paper, 2018). A disease characterized by the build-up of fatty material and calcium deposition in the arterial wall resulting in partial or complete occlusion of the arterial lumen. "In mice, decreased IDH2 expression contributes to atherosclerosis progression by increasing oxidative stress." (PMID 30327580, 2018).
benign cartilage tumours (1 paper, 2023). "The high frequency of IDH1 and IDH2 (collectively referred to as IDH) mutations in benign cartilage tumours indicates that these mutations occur early in tumourigenesis, suggesting that IDH mutations have an important driver role in the formation of cartilage tumours." (PMID 37509266, 2023).
bone sarcoma (1 paper, 2025). A sarcoma that arises from the bone.
brain astrocytoma (1 paper, 2020). A astrocytoma (excluding glioblastoma) that involves the brain. "In contrast to brain astrocytomas, no hotspot IDH1 p.R132H or IDH2 p.R172H mutations were identified, and none of our cases harbored the 1p19q codeletion." (PMID 32771057, 2020).
brainstem glioma (1 paper, 2025). "In the present case, a dramatic response to radiation and temozolomide treatment and subsequent improved hearing were observed in a rare IDH2 R172S-mutant brainstem glioma patient who presented with left hearing loss." (PMID 40697380, 2025). "Marked improvement of hearing was observed after TMZ and radiation treatment in a rare IDH2 R172S-mutant, adult brainstem glioma case." (PMID 40697380, 2025). "Here, we present a case of adult brainstem glioma with non-canonical IDH2 mutation and treatment response to radiation and TMZ." (PMID 40697380, 2025). "A couple of studies have shown that mutations in IDH1 and IDH2 genes can be found in 18-31% of adult brainstem gliomas and that a majority of these mutations are non-canonical IDH1/2-mutations, compared to a high frequency of IDH1 R132H mutations in IDH-mutant supratentorial diffuse gliomas." (PMID 40697380, 2025).
Burkitt lymphoma (1 paper, 2024). A rare form of malignant mature B-cell non-Hodgkin lymphoma. "The combination of FDA-approved PIs with a pharmacological IDH2 inhibitor (AGI-6780) triggered synergistic cytotoxicity in MM, MCL, and Burkitt’s lymphoma (BL) cell lines." (PMID 38500772, 2024).
cardiac arrest (1 paper, 2025). Cessation of breathing and/or cardiac function. "Overall, Epsa1, Hif3a, and Idh2 demonstrated significant diagnostic value, suggesting that they could be considered as potential drug targets for diagnosing the regulation of hippocampal neuron mitochondria in rats after heparin-induced cardiac arrest and cardiopulmonary resuscitation." (PMID 41585220, 2025). "To determine the potential value of the three key genes, Epsa1, Idh2, and Hif3a, in regulating the mitochondria of hippocampal neurons in rats after heparin-induced cardiac arrest and cardiopulmonary resuscitation, we conducted a receiver operating characteristic (ROC) analysis." (PMID 41585220, 2025).
chromophobe carcinoma (1 paper, 2018). "In contrast to expectations based on these studies, we observed a strong IDH2 expression by immunohistology in oncocytomas and to a lesser degree in eosinophilic/oncocytic variants of chromophobe carcinoma by TMA." (PMID 30116406, 2018). "IDH2 was strongly positive in oncocytoma (18/20) and in the eosinophilic/oncocytic variant of chromophobe renal cell carcinoma (5/20)." (PMID 30116406, 2018).
Cirrhosis (1 paper, 2025). A chronic disorder of the liver in which liver tissue becomes scarred and is partially replaced by regenerative nodules and fibrotic tissue resulting in loss of liver function. "In addition, we observed a trend of decrease in SIRT3 (P = 0.06) and IDH2 (P = 0.05) expression in MASLD and fibrosis, with the most pronounced reduction in patients with cirrhosis." (PMID 41258072, 2025).
colitis (1 paper, 2019). Inflammation of the colon. "Multiple studies have demonstrated the implications of IDH2 in diverse disease models, such as colitis and non-alcoholic liver disease." (PMID 31546946, 2019).
D-2-hydroxyglutaric aciduria (1 paper, 2016). D-2-hydroxyglutaric aciduria (D-2-HGA) is a rare clinically variable neurological form of 2-hydroxyglutaric aciduria characterized biochemically by elevated D-2-hydroxyglutaric acid (D-2-HG) in the urine, plasma and cerebrospinal fluid. "D-2-hydroxyglutaric aciduria (D2HGA) type II is a rare neurometabolic disorder caused by germline gain-of-function mutations in isocitrate dehydrogenase 2 (IDH2), resulting in accumulation of D-2-hydroxyglutarate (D2HG)." (PMID 27469509, 2016).
depression (1 paper, 2019). "Further statistical analysis demonstrated that Por, Idh2, and Esd were significantly down-regulated in the depression-susceptible group as compared with the control group." (PMID 31624233, 2019).
diabetic retinopathy (1 paper, 2025). "Our findings reveal a dual-stress pattern in diabetic retinopathy: mitochondrial compromise marked by IDH2 and MGST1 suppression, and a sulfur-driven antioxidant defense through Nrf2 activation." (PMID 41334440, 2025).
dilated cardiomyopathy (1 paper, 2021). Cardiomyopathy which is characterized by dilation and contractile dysfunction of the left and right ventricles. "Moreover, transgenic mice with global expression of mutant IDH2 develop dilated cardiomyopathy accompanied with elevated R-2HG levels, while in turn, silencing of mutant IDH2 expression restored cardiac function by lowering R-2HG levels." (PMID 32948843, 2021).
edema (1 paper, 2025). An abnormal accumulation of fluid beneath the skin, or in one or more cavities of the body. "Heparin precisely targets this pathway by upregulating Epsa1, restoring Idh2 activity, and stabilizing Hif3a, thereby enhancing Pink1/Parkin-mediated mitophagy to eliminate impaired mitochondria, suppress sustained inflammatory activation, and ultimately reduce neuronal apoptosis and cerebral edema." (PMID 41585220, 2025).
endothelial dysfunction (1 paper, 2022). In vascular diseases, endothelial dysfunction is a systemic pathological state of the endothelium (the inner lining of blood vessels) and can be broadly defined as an imbalance between vasodilating and vasoconstricting substances produced by (or acting on) the endothelium. "In our previous study, we have shown that mitochondrial dysfunction in IDH2 deficiency condition ultimately leads to endothelial dysfunction as demonstrated by impaired vascular function." (PMID 35052866, 2022).
Fibroadenoma (1 paper, 2024). A benign tumor of the breast characterized by the presence of stromal and epithelial elements. "The data indicated that the protein level of IDH2 in TNBC was much higher than that in Her2+, luminal B and fibroadenoma, and importantly, benign fibroadenoma had the lowest level of IDH2." (PMID 38413708, 2024). "Furthermore, we analyzed the protein levels of IDH2 among fibroadenoma, luminal A, luminal B, Her2+ and TNBC tissue samples." (PMID 38413708, 2024).
in situ carcinoma (1 paper, 2012). A malignant epithelial neoplasm which is confined to the epithelial layer without evidence of further tissue invasion. "Within this analysis, we observed that IDH2 expression was significantly downregulated in in situ carcinoma and upregulated in infiltrating carcinoma compared with peritumor tissues." (PMID 23226729, 2012). "In this study, we observed that IDH2 gene expression was significantly downregulated in early stage (in situ carcinoma) but upregulated in advanced stage (infiltrating carcinoma) CRC compared to peritumor tissue by cDNA microarray and may play a role in tumorigenesis of the disease." (PMID 23226729, 2012).
Kashin-Beck disease (1 paper, 2012). Disabling osteochondrodysplasia with osteosclerosis, cone-shaped metaphysis, and shortening of the diaphysis. "The overexpression of IDH2 has been reported in endometrial, prostate and testicular cancer as well as in Kashin-Beck disease." (PMID 23226729, 2012).
large cell neuroendocrine carcinoma (1 paper, 2022). A usually aggressive carcinoma composed of large malignant cells which display neuroendocrine characteristics. "Interestingly, IDH2 mutations may be present even in large-cell neuroendocrine carcinomas, sharing with IDH2-mutant SNUC also similar cancer signaling pathways." (PMID 35059992, 2022).
Lewis lung carcinoma (1 paper, 2017). "Therefore, we evaluated the role of idh2 in acrolein-induced lung injury using idh2 short hairpin RNA- (shRNA-) transfected Lewis lung carcinoma (LLC) cells and idh2-deficient (idh2−/−) mice." (PMID 29456784, 2017).
liver fibrosis (1 paper, 2020). "Our studies elucidate a new approach for blocking the progression of liver fibrosis through the regulation of α-ketoglutarate and IDH2 in HSCs; however, further studies are still required." (PMID 32124915, 2020). "The present study suggests that IDH2 and α-ketoglutarate may be potential new targets for the prevention and treatment of liver fibrosis." (PMID 32124915, 2020).
lung disease (1 paper, 2017). "Having established the importance of IDH2 in the regulation of redox status and in lung tissue functions, we hereby propose that downregulation of idh2 in both in vitro and in vivo systems could be an effective model for future lung disease research." (PMID 29456784, 2017).
lung injury (1 paper, 2017). "The findings of the present study support a significant role for increased ROS resulting from disruption of mitochondrial antioxidant defense via suppression of IDH2 expression in acrolein-induced acute lung injury." (PMID 29456784, 2017).
marginal zone lymphoma (1 paper, 2024). A usually indolent mature B-cell lymphoma, arising from the marginal zone of lymphoid tissues. "Additionally, a patient sample of marginal zone lymphoma also showed increased sensitivity to venetoclax when combined with IDH2 inhibition." (PMID 38893249, 2024).
meningioma (1 paper, 2012). A generally slow growing tumor attached to the dura mater. "Only one other sample, also a meningioma, recorded an average methylation at the IDH2 promoter above 5%." (PMID 23267435, 2012). "For IDH2, average methylation across all tumor samples was 2.3%, and the highest average methylation across the eight CpGs assayed shown by any sample was 7.1% in a meningioma (Table A1 in Appendix)." (PMID 23267435, 2012).